RNU6-575P (RNA, U6 small nuclear 575, pseudogene)
Gene: Small nuclear RNA gene on chromosome 7 (43,207,762 to 43,207,866, reverse strand). Ensembl gene ENSG00000223258.
Homologues: Orthologues: chimpanzee U6 (98% identical), macaque U6 (88% identical), rat LOC120098671 (71% identical), mouse Gm26159 (70% identical), pig U6 (69% identical), dog U6 (66% identical). Paralogues in human: RNU6-15P (80% identical), RNU6-618P (80% identical), RNU6-1060P (79% identical), RNU6-14P (79% identical), RNU6-154P (79% identical), RNU6-1 (78% identical), RNU6-1011P (78% identical), RNU6-1042P (78% identical), RNU6-1048P (78% identical), RNU6-10P (78% identical), RNU6-1122P (78% identical), RNU6-1152P (78% identical), and 1286 more.